USP3 (ubiquitin specific peptidase 3)
Description:
Deubiquitinase that plays a role in several cellular processes including transcriptional regulation, cell cycle progression or innate immunity. In response to DNA damage, deubiquitinates monoubiquitinated target proteins such as histone H2A and H2AX and thereby counteracts RNF168- and RNF8-mediated ubiquitination. In turn, participates in the recruitment of DNA damage repair factors to DNA break sites. Required for proper progression through S phase and subsequent mitotic entry. Participates in establishing tolerance innate immune memory through non-transcriptional feedback. Mechanistically, negatively regulates TLR-induced NF-kappa-B signaling by targeting and removing the 'Lys-63'-linked polyubiquitin chains on MYD88. Negatively regulates the activation of type I interferon signaling by mediating 'Lys-63'-linked polyubiquitin chains on RIGI and IFIH1. Also deubiquitinates ASC/PYCARD, the central adapter mediating the assembly and activation of most inflammasomes, and thereby promotes inflammasome activation.
Synonyms: SIH003; UBP
Tractability: PROTAC: ubiquitination databases record sites on it; its protein half-life has been measured.
Target class: Enzyme; Hydrolase
Gene: Protein-coding gene on chromosome 15 (63,504,501 to 63,594,640, forward strand). Ensembl gene ENSG00000140455.
Subcellular location: Nucleus; Cytoplasm
Subcellular location (Human Protein Atlas): Nucleoplasm; Midbody ring
Pathways (Reactome):
Metabolism of proteins: Ub-specific processing proteases
Gene Ontology:
Molecular function: cysteine-type deubiquitinase activity; histone binding; histone H2A deubiquitinase activity; histone H2B deubiquitinase activity; zinc ion binding
Biological process: DNA repair; DNA repair-dependent chromatin remodeling; protein deubiquitination
Cellular component: chromatin; cytoplasm; nucleoplasm; nucleus
Genetic constraint (gnomAD): Loss-of-function variants: 20 observed, 63.79 expected, observed/expected ratio (o/e) 0.31, 90% interval 0.22 to 0.46. The upper end of that interval is the gene's LOEUF score, 0.46, which puts it in group 2 of 6, group 1 being the genes least tolerant of losing a copy. Missense variants: 464 observed, 623.53 expected, observed/expected ratio (o/e) 0.74, 90% interval 0.69 to 0.8. Synonymous variants: 214 observed, 225.03 expected, observed/expected ratio (o/e) 0.95, 90% interval 0.85 to 1.07.
Homologues: Orthologues: chimpanzee USP3 (99% identical), dog USP3 (98% identical), mouse Usp3 (97% identical), guinea pig USP3 (96% identical), macaque USP3 (94% identical), rabbit USP3 (92% identical), pig USP3 (90% identical), rat Usp3 (88% identical), tropical clawed frog usp3 (88% identical), zebrafish usp3 (74% identical). Paralogues in human: USP44 (36% identical), USP49 (35% identical), USP33 (29% identical), USP20 (28% identical), USP22 (24% identical), USP4 (24% identical), USP16 (23% identical), USP2 (23% identical), USP51 (23% identical), USP19 (23% identical), USP32 (23% identical), USP45 (23% identical), and 59 more.
Diseases named in the same sentence as USP3 in open-access papers:
USP3 is named in the same sentence as 38 diseases in open-access papers, as found by Europe PMC text mining. Sharing a sentence is not in itself a finding about the gene and the disease. The quoted sentences say what the papers report.
gastric cancer (13 papers, 2017 to 2025). A primary or metastatic malignant neoplasm involving the stomach. "Studies have shown that the expression of USP3 is significantly elevated in several cancers, including gastric cancer, lung cancer and colorectal cancer, and that high expression of USP3 is closely associated with poor patient prognosis." (PMID 38531846, 2024). "Also, overexpression of USP3 has been associated with gastric cancer tumorigenesis." (PMID 31546954, 2019). "The overexpression of USP3 leads to an unfavorable prognosis in breast cancer patients and stomach cancer metastasis." (PMID 38898455, 2024). "USP3 can accelerate gastric cancer metastasis by enhancing the COL9A3/COL6A5 stability via deubiquitination." (PMID 37980532, 2023). "For example, the expression of USP3 is highly elevated in gastric cancer, promoting the invasion and migration of gastric cancer cells." (PMID 37170124, 2023). "Our previous study revealed that USP3 promotes tumour progression and is highly expressed in gastric cancer (GC)." (PMID 34930901, 2021). "Moreover, USP3 interacts with SUZ12 in gastric cancer and regulates the homeostasis of SUZ12 through deubiquitylation, thereby promoting the migration and invasion of gastric cancer cells." (PMID 38531846, 2024). "Increasing evidence suggests a significant role for USP3 in the progression of gastric cancer." (PMID 38773075, 2024). "Similarly, USP3 was reported to promote the gastric cancer progression and metastasis by deubiquitinating COL9A3 and COL6A5." (PMID 37322017, 2023). "USP3 regulates COL9A3/COL6A5 stabilisation to promote gastric cancer progression." (PMID 36766336, 2023). "In addition, USP3 is aberrantly expressed in a wide range of cancers, such as gastric cancer, glioblastoma and neuroblastoma, implicating that USP3 could be an effective target for targeted therapies." (PMID 38773075, 2024). "Moreover, USP3 is significantly upregulated in glioblastomas and gastric cancer (GC)." (PMID 32268558, 2020). "The elevated USP3 expression can affect the abundance of COL9A3 and COL6A5, thereby promoting tumor proliferation and migration of gastric cancer cells." (PMID 39759114, 2025). "The deubiquitination enzyme USP3, an essential mediator regulating oncogenic activity both in vitro and in vivo, can deubiquitinate COL9A3 and COL6A5 in gastric cancer cells." (PMID 39759114, 2025). "Additionally, lower USP3 mRNA expression predicted a worse prognosis not only for CRC patients, but also for patients with other malignancies, such as gastric cancer, lung cancer and breast cancer." (PMID 28655924, 2017).
breast carcinoma (8 papers, 2017 to 2024). "Three DUBs, including ATXN3L, BAP1, and USP3 can deubiquitinate and stabilize KLF5 that are implicated in the pathological development of breast cancer." (PMID 38468288, 2024). "USP3 promotes gallbladder cancer proliferation by modifying the deubiquitination level of pyruvate kinase L/R, and USP3 facilitates breast cancer progression through KLF5 deubiquitination." (PMID 38531846, 2024). "USP3 is also responsible for the stabilization of Klf5 that inhibits cell cycle inhibitor p27, promoting cellular proliferation in breast cancer HCC1937, HCC1806 and SUM149PT cells." (PMID 34577547, 2021). "Besides UCHL1, some other DUBs, such as ATXN3L, BAP1, and USP3 can deubiquitinate KLF5 and are implicated in the pathological development of breast cancer." (PMID 38468288, 2024). "For example, USP3 facilitates breast cancer cell growth via deubiquitinating KLF5." (PMID 37980532, 2023). "Klf5 is highly expressed in breast cancer, possibly indicating that USP3 may play a regulatory role in cancer proliferation." (PMID 34577547, 2021). "Notably, USP3 individually makes breast cancer cells resistant to drugs." (PMID 38773075, 2024). "USP3 is dependent on KLF5 and ectopic expression of KLF5 partially rescues the proliferation inhibiting effect of USP3 knockdown in breast cancer cells in vitro and tumorigenesis in vivo." (PMID 38773075, 2024). "According to the literature review, USP3 promotes GC cell migration and invasion; SLC7A6 hasn’t been reported in studies related to cancer; IGF2BP1 accelerates GC progression; and TKT facilitates breast cancer metastasis." (PMID 35739527, 2022).
neuroblastoma (7 papers, 2021 to 2025). Neuroblastoma (NB) is the most common solid, extracranial childhood tumor. "In contrast, loss of USP3 reduced neuroblastoma cell proliferation, migration, and invasion in vitro, and suppressed tumor growth in vivo." (PMID 37170124, 2023). "Taken together, our results suggest that the loss of USP3 abolishes REST-mediated neuroblastoma tumor formation and growth in vitro and in vivo." (PMID 37170124, 2023). "Despite considerable study of USP3 regulation in a variety of biological behaviors in several malignancies, the underlying molecular mechanism of USP3 regulating neuroblastoma differentiation and tumorigenesis remains elusive." (PMID 37170124, 2023). "The loss-of-function-based screening for DUB genes identified USP3 as a regulator of REST protein levels in neuroblastoma." (PMID 37170124, 2023). "A loss of USP3 led to attenuation of REST-mediated neuroblastoma tumorigenesis in a mouse xenograft model." (PMID 37170124, 2023). "Moreover, western blot analysis and immunofluorescence staining demonstrated that the loss of USP3 in the neuroblastoma cell line showed a significant decrease in REST protein levels compared with the mock control." (PMID 37170124, 2023). "We observed that the impact of USP3 gene expression was highest with a z-score of + 5.95 (p < 0.001) in neuroblastoma, indicating that high expression of the USP3 gene may be associated with poor outcomes in neuroblastoma patients." (PMID 37170124, 2023). "Among neuroblastoma patients, the m5C reader ALYREF forms a nuclear coactivator complex alongside MYCN, thereby prompting USP3 transcription and fostering neuroblastoma tumourigenesis." (PMID 40008496, 2025). "To investigate the effect of USP3 on REST-mediated progression of SH-SY5Y neuroblastoma tumors, we used the USP3-KO clone showing a low REST protein level." (PMID 37170124, 2023). "Conversely, USP3 over-expression in USP3-silenced cells increased the cell proliferation of neuroblastoma cells." (PMID 37170124, 2023). "We analyzed the expression of USP3 using two individual publicly available neuroblastoma datasets (Versteeg, and Hiyama)." (PMID 37170124, 2023). "Altogether, our results elucidate a novel mechanism of USP3-mediated regulation of REST protein levels in regulating neuroblastoma cell differentiation, self-renewal, and tumorigenesis." (PMID 37170124, 2023). "As expected, the USP3-silenced neuroblastoma cells reconstituted with either USP3 or REST regained its carcinogenic behavior." (PMID 37170124, 2023). "The USP3 mRNA expression level was significantly higher in the neuroblastoma compared to the normal brain tissue samples, suggesting that USP3 is aberrantly expressed in neuroblastoma tissues." (PMID 37170124, 2023). "The shRNA-targeting USP3-transfected in the neuroblastoma cells showed a significant reduction in USP3 and REST protein level." (PMID 37170124, 2023). "Altogether, our results suggest that USP3 is critical in maintaining an abundance of REST protein to determine neuroblastoma differentiation." (PMID 37170124, 2023). "USP3-mediated stabilization of REST contributed to the maintenance of the self-renewal ability in neuroblastoma." (PMID 37170124, 2023). "The findings of this study indicate that USP3 is a critical factor that blocks neuronal differentiation, which can lead to neuroblastoma." (PMID 37170124, 2023). "We next analyzed the ubiquitination status of REST to further gain insight into the role of USP3-mediated REST protein stabilization during differentiation of neuroblastoma cells." (PMID 37170124, 2023). "We observed that high scores for USP3 mRNA expression corresponded to high mRNA expression of REST in a majority of the neuroblastoma cell lines." (PMID 37170124, 2023).
neuroblastoma (continued). "Given that USP3 is involved in increasing MYCN and snail protein levels, which are key transcriptional factors that regulate neuronal tumors, in this study we explore the post-translational role of USP3 on REST protein during neuroblastoma tumorigenesis." (PMID 37170124, 2023). "Silencing of USP3 led to a decreased self-renewal capacity and promoted retinoic acid-induced differentiation in neuroblastoma." (PMID 37170124, 2023). "In contrast, in USP3-silenced neuroblastoma cells, a seeding density of > 10 cells per well was required to form neurospheres in at least 50% of the wells." (PMID 37170124, 2023). "In neuroblastoma patients, the m5C reader ALYREF forms a nuclear coactivator complex with MYCN to stimulate USP3 transcription, which promotes the tumorigenesis of neuroblastoma." (PMID 37325635, 2023). "Next, we investigated the effect of USP3 downregulation on clonogenic growth ability in neuroblastoma cells by performing an in vitro limiting, dilution neurosphere formation assay." (PMID 37170124, 2023). "Next, we performed a subcutaneous tumorigenesis assay to corroborate the role of USP3 on the REST-mediated oncogenic transformation in neuroblastoma in vivo." (PMID 37170124, 2023). "We also observed that neuroblastoma cell lines showed marked dependency on USP3 for cell viability, especially in the MYCN-amplified context." (PMID 33767157, 2021). "Consistent with an MYCN-ALYREF-USP3 signal driving neuroblastoma tumorigenesis, we found that high USP3 mRNA expression in the SEQC neuroblastoma patient cohort (n = 498) also correlated with poor prognosis." (PMID 33767157, 2021). "ALYREF contributed to neuroblastoma cell proliferation by blocking MYCN degradation through direct transcriptional upregulation of USP3, a deubiquitinating enzyme." (PMID 33767157, 2021). "By further examining pan-cancer cell line gene expression (RNA-seq) profiles using Cancer Cell Line Encyclopedia (CCLE)/Cancer Dependency Map33 we observed that neuroblastoma cell lines had the highest USP3 gene expression compared with all other cancer types." (PMID 33767157, 2021). "We further investigated the phenotypic effect of USP3 knockdown in MYCN-amplified neuroblastoma cell lines with high USP3 expression." (PMID 33767157, 2021). "A recent article found that USP3 can also regulate tumor self-renewal and proliferative capacity by interacting with the repressor element-1 (RE-1) silencing transcription factor (REST) in neuroblastoma, further demonstrating that USP3 is a potential prognostic marker for neuroblastoma." (PMID 38773075, 2024). "Thus, to elucidate the regulatory mechanism of REST degradation by USP3 in neuroblastoma, we performed an in silico analysis of the entire USP gene expression in neuroblastoma." (PMID 37170124, 2023). "To validate whether USP3 could increase the REST protein levels, we transfected the neuroblastoma cells with an increasing concentration of Flag-USP3 and catalytic mutant Flag-USP3CS." (PMID 37170124, 2023). "However, a loss of USP3 eventually reduces the REST protein level and promotes efficient neuroblastoma differentiation." (PMID 37170124, 2023). "Together, these data suggest that USP3 is a potential prognostic marker in neuroblastoma." (PMID 37170124, 2023). "Interestingly, the USP3 mRNA levels were observed to be significantly higher in the neuroblastoma cell lines when compared with other cancer cell lines." (PMID 37170124, 2023). "We envision that targeting USP3 in neuroblastoma tumors might provide an effective therapeutic differentiation strategy for improved survival rates of neuroblastoma patients." (PMID 37170124, 2023). "USP3 was one of the most highly expressed DUB candidates in neuroblastoma." (PMID 37170124, 2023). "Thus, we investigated the impact of USP3-mediated downregulation of the REST protein level on self-renewal behavior in human neuroblastoma." (PMID 37170124, 2023).
neuroblastoma (continued). "However, the cell migration, cell invasion, and colony formation were significantly restored when USP3-depleted neuroblastoma cells were reconstituted with either USP3 or REST." (PMID 37170124, 2023). "Finally, USP3 gene knockout using a CRISPR/Cas9 system in neuroblastoma cell lines resulted in reduced cell viability, anchorage-independent growth, migration, and invasion." (PMID 37170124, 2023). "Moreover, USP3 downregulation in neuroblastoma cell lines significantly decreased the number and size of the neurosphere." (PMID 37170124, 2023). "Additionally, we cross confirmed these carcinogenesis activities in USP3-silenced SK-N-SH neuroblastoma cells and reconstituted with either USP3 or REST." (PMID 37170124, 2023). "Additionally, RT-PCR analysis of TUJ1, a neuronal differentiation marker, showed a significant increase, whereas NESTIN, a neural stem cell marker showed a significantly decreased expression in USP3-silenced neuroblastomas." (PMID 37170124, 2023). "Furthermore, we found that USP3 regulates self-renewal and promotes RA-induced differentiation in neuroblastoma tumors." (PMID 37170124, 2023). "In addition, morphological variability was found, suggesting that the downregulation of USP3 impedes neuroblastoma clonogenic growth." (PMID 37170124, 2023). "USP3 is one of the top candidates for high expression in neuroblastoma." (PMID 37170124, 2023). "Furthermore, silencing of USP3 triggered REST protein degradation that promoted neuroblastoma differentiation." (PMID 37170124, 2023). "A reduced expression level of Oct4, SOX2 and NESTIN was found, whereas TrkA, TH, MAP2 and TUJ1 was increased in USP3-silenced cells, suggesting that USP3 downregulation might impair self-renewal capacity in neuroblastoma." (PMID 37170124, 2023). "However, USP3-depleted neuroblastoma cells, when reconstituted with USP3, resulted in an increase in the number and size of the neurospheres and were rescued from any morphological abnormalities in the neurospheres." (PMID 37170124, 2023). "However, USP3-silenced neuroblastoma cell lines reconstituted with USP3 showed an improved neurosphere forming ability." (PMID 37170124, 2023). "To further examine ALYREF as a transcriptional coactivator for MYCN, we evaluated the effect of ALYREF knockdown on USP3 gene transcription in SHEPMYCN3 neuroblastoma cells, which express MYCN under the control of doxycycline, therefore minimising ALYREF knockdown effects on MYCN stability." (PMID 33767157, 2021). "Knockdown of USP3 had marked effects on the cancer phenotype in MYCN-amplified neuroblastoma cells." (PMID 33767157, 2021). "Thus, we envision that USP3 could be a potential alternative therapeutic target for neuroblastoma treatment." (PMID 37170124, 2023). "We generated single-cell-derived USP3 KO clones using the CRISPR-Cas9 system in the SH-SY5Y neuroblastoma cell line, which is a well-established cell line for studying neuroblastoma tumor progression." (PMID 37170124, 2023). "The USP3 gene knockout in neuroblastoma cells was performed using CRISPR/Cas9, and the clinical relevance of USP3 regulating REST-mediated neuroblastoma tumorigenesis was confirmed by in vitro and in vivo oncogenic experiments." (PMID 37170124, 2023). "The result showed that USP3 and REST expression was high in undifferentiated neuroblastoma tumors when compared to well-differentiated neuroblastoma tumors." (PMID 37170124, 2023). "An in silico analysis showed a correlation between USP3 and REST in multiple neuroblastoma cell lines and identified USP3 as a prognostic marker for overall survival in neuroblastoma patients." (PMID 37170124, 2023). "Overall, these results indicate that USP3 is critical in regulating REST protein level to maintain self-renewal and proliferation ability in neuroblastoma." (PMID 37170124, 2023). "We first analyzed the expression level of USP3 and REST in undifferentiated and differentiated neuroblastoma using a TARGET dataset." (PMID 37170124, 2023).